GSDMD (gasdermin D)
Diseases named in the same sentence as GSDMD in open-access papers (continued):
Sharing a sentence is not in itself a finding about the gene and the disease.
retinal degeneration (2 papers, 2020 to 2023). Degeneration of the retina. "This work has demonstrated an important function of the pyroptotic pore-forming protein GSDMD in mediating inflammatory responses underlying the progression of retinal degenerations." (PMID 37864169, 2023). "Mice deficient in GSDMD function were found to have significantly preserved retinal function, increased photoreceptor survivability, and decreased inflammation compared to controls following photo-oxidative damage-induced retinal degeneration." (PMID 37864169, 2023). "To further elucidate the contribution of GSDMD in the progression of retinal degeneration, we assessed the retinal function and histology of GsdmdI105N/I105N mice in both DR conditions and following 5 days of PD, compared to WT controls." (PMID 37864169, 2023). "This study, therefore, aims to investigate the role of GSDMD in the retina during health and degeneration using an in-vivo photo-oxidative damage (PD)-induced model of retinal degeneration." (PMID 37864169, 2023). "Results from this work strongly support a role for GSDMD in the pathogenesis of retinal degeneration, with GSDMD-mutant mice demonstrating improved retinal function, reduced levels of cell death and inflammation." (PMID 37864169, 2023). "Further research into the role of both Gasdermin D and pyroptosis in the progression of retinal degenerations however, is necessary, in addition to exploring the therapeutic targeting of CASP-1." (PMID 32041990, 2020). "GSDMD mutant and knockout mice, in vitro models of inflammation and a well-established in vivo model of retinal degeneration (photo-oxidative damage; PD) were utilised to explore the role and pathological contribution of GSDMD in regulating IL-1β release and propagating retinal inflammation." (PMID 37864169, 2023). "Targeting GSDMD using genetic or pharmacological inhibitors may pose a therapeutic opportunity to dampen inflammatory cascades and delay the progression of retinal degeneration." (PMID 37864169, 2023). "Overall, we demonstrate increased retinal expression of GSDMD in degeneration, and show that inhibition of GSDMD function in-vivo animal models of retinal degeneration and in-vitro reduces release of pro-inflammatory cytokine IL-1β, providing overall protection." (PMID 37864169, 2023). "This provides a new mechanism for GSDMD-mediated retinal degeneration, where IL-1β may be packaged and sent to distant cells via EV to propagate inflammation." (PMID 37864169, 2023). "Investigations into the role of GSDMD in the retina, including characterising protein expression and release of pro-inflammatory cytokines, is, therefore, necessary to understand its contribution to chronic inflammation in retinal degenerations, including AMD." (PMID 37864169, 2023). "Hence, improving our mechanistic understanding of tissue or cell-specific regulation of individual inflammasome components, such as GSDMD, its related proteins, and the downstream mechanisms is imperative for developing specific and targeted therapeutics for various retinal degeneration." (PMID 37864169, 2023). "Taken together these results indicate that impairing production of GSDMD is not protective against PD-induced retinal degeneration." (PMID 37864169, 2023). "We suggest that in retinal degenerations, CASP-1 propagates retinal inflammation and photoreceptor cell death via the cleavage and activation of pro-inflammatory cytokine IL-1β as well as possibly through its role in Gasdermin D pyroptotic pore formation." (PMID 32041990, 2020).
retinal ischemia (2 papers, 2020 to 2023). A ischemic disease that involves the retina. "This conclusion was made despite our data indicating the key roles of CASP1 and GSDMD in RGC death, which are typically associated with pyroptotic death in the retinal ischemia model." (PMID 37998361, 2023). "Our findings reveal the unique effect of CASP8 on pyroptosis: CASP8 initiates GSDMD-predominant pyroptosis during retinal ischemia, in accordance with the results during pathogen infection." (PMID 32295623, 2020).
retinopathy of prematurity (2 papers, 2023). A bilateral retinopathy characterized by neovascularization, scarring, retinal detachment, and eventually blindness. "Most recently, we have demonstrated that GSDMD gene knockout (KO) ameliorated hyperoxia-induced BPD and retinopathy of prematurity (ROP) in mouse models, indicating a critical role for GSDMD in hyperoxia-induced preterm multi-organ injury." (PMID 37398125, 2023).
schizophrenia (2 papers, 2025). A major psychotic disorder characterized by abnormalities in the perception or expression of reality. "Our clinical data showed that pyroptosis-related genes, including CASP1, GSDMD, and IL1B, were significantly elevated in patients with schizophrenia and positively correlated with HERV-W env expression." (PMID 39859234, 2025). "Our clinical observations revealed that the levels of CASP1, GSDMD, and IL1B were significantly elevated in the blood of patients with schizophrenia and positively correlated with HERV-W env." (PMID 39859234, 2025). "In this study, we found that the expression levels of pyroptosis-related genes, specifically CASP1, GSDMD (Gasdermin D), and IL1B, were significantly elevated in patients with schizophrenia compared to healthy controls." (PMID 39859234, 2025). "Our clinical findings indicate a strong association between HERV-W env and the pyroptosis-related genes CASP1, GSDMD, and IL1B in individuals with schizophrenia." (PMID 39859234, 2025). "In this study, we discovered that HERV-W env promotes pyroptosis by increasing the expression of NLRP3, CASP1, GSDMD and IL1B, potentially representing a novel mechanism by which HERV-W env influences neuronal cell death in patients with schizophrenia." (PMID 39859234, 2025). "Clinical studies have shown elevated levels of CASP1, GSDMD, and IL1B in the blood of schizophrenia patients, highlighting their role in the classical pyroptosis pathway." (PMID 39859234, 2025). "Similarly, HERV-W env upregulates NLRP3, CASP1, and GSDMD expression, promoting lactate dehydrogenase (LDH) and IL-1β release and inducing CASP1–GSDMD-dependent neuron pyroptosis in recent-onset schizophrenia." (PMID 41200560, 2025). "Moreover, our clinical data revealed that the levels of CASP1, GSDMD, and IL1B in the blood of schizophrenia patients were significantly higher than those in healthy controls, consistent with the prediction from bioinformatics analysis of GSE25673." (PMID 39859234, 2025). "Additionally, Spearman’s analysis demonstrated that HERV-W env positively correlated with CASP1 (r = 0.7156), GSDMD (r = 0.7690), and IL1B (r = 0.6172) in the blood of schizophrenia patients." (PMID 39859234, 2025).
septic shock (2 papers, 2023 to 2024). Shock caused by infection; frequently caused by gram negative bacteria, although some cases have been caused by other bacteria, viruses, fungi, and protozoa; characterized by fever, chills, tachycardia, tachypnea, and hypotension. "Our study confirmed that septic shock induced myocardial pyroptosis through NLRP3 inflammasome/Caspase-1/GSDMD pathway, and inhibition of pyroptosis was found to alleviate septic shock-induced cardiac dysfunction." (PMID 36992838, 2023).
skin cancer (2 papers, 2021 to 2024). "While MPs stimulation in normal cells induces pyroptosis mediated by GSDMD, in skin cancer cells pyroptosis does not occur because the expression of GSDMD is too low." (PMID 39518141, 2024).
sterile (2 papers, 2020 to 2022). "Pore forming ability of GSDMD represents a drug target to block IL-1β release during inflammasome-driven sterile inflammatory diseases." (PMID 36045672, 2022).
Streptococcus pneumoniae infection (2 papers, 2025). "GSDMD can also mediate the scorch death of pulmonary macrophages caused by Streptococcus pneumoniae infection." (PMID 40704967, 2025). "GSDMD can mediate pyroptosis of pulmonary macrophages caused by Streptococcus pneumoniae infection." (PMID 40704967, 2025).
thyroid cancer (2 papers, 2024 to 2025). "Additionally, by integrating data from ATC-containing samples in the NCBI database, we found that GSDME (DFNA5) was significantly upregulated in ATC samples compared to normal thyroid (NT) and other types of thyroid cancer, whereas GSDMD did not exhibit a consistent upregulation trend." (PMID 40978473, 2025).
tuberculosis (2 papers, 2022 to 2025). A chronic, recurrent infection caused by the bacterium Mycobacterium tuberculosis. "Therefore, ASTA inhibits inflammation-induced pyroptosis by inhibiting the caspase 4/11-gasdermin D pathway and has the potential to protect lung tissue from tuberculosis-related inflammatory injury." (PMID 36523416, 2022).
Ureteral obstruction (2 papers, 2022 to 2023). Obstruction of the flow of urine through the ureter. "Our study consistently suggested that Casp11/GSDMD were required for NETs formation in the kidneys after ureteral obstruction." (PMID 35941120, 2022). "Herein, we showed that unilateral ureteral obstruction (UUO) induced Gasdermin D (GSDMD) activation in neutrophils, abundant neutrophil extracellular traps (NETs) formation and macrophage-to-myofibroblast transition (MMT) characterized by α-smooth muscle actin (α-SMA) expression in macrophages." (PMID 35941120, 2022). "Thus, in response to ureteral obstruction, NETs formation in the renal infiltrating neutrophils depends on Casp11/GSDMD activation." (PMID 35941120, 2022).
vascular dementia (2 papers, 2021 to 2025). A degenerative vascular disorder affecting the brain. "Moreover, it exacerbates vascular dementia by producing IL-18, IL-1β, and the N-terminal fragment of GSDMD, which also contributes to neuronal cell death." (PMID 40326096, 2025).
acute coronary syndrome (1 paper, 2022). Signs and symptoms related to acute ischemia of the myocardium secondary to coronary artery disease. "In acute coronary syndrome (ACS), the overexpression or inhibition of IRF-1 effectively modulated caspase-1 activation, macrophage lysis and GSDMD expression, suggesting that IRF-1 potently activates ox-LDL-induced macrophage pyroptosis." (PMID 36544106, 2022).
acute lymphoblastic leukemia (1 paper, 2025). Leukemia with an acute onset, characterized by the presence of lymphoblasts in the bone marrow and the peripheral blood. "For instance, S100A8/A9 heterodimers have been shown to drive GSDMD-dependent pyroptosis in acute lymphoblastic leukemia (ALL), while FLOT1 promotes AML progression through dual suppression of pyroptosis and apoptosis." (PMID 41267084, 2025).
adenoid cystic carcinoma (1 paper, 2022). A malignant tumor arising from the epithelial cells. "However, in adenoid cystic carcinoma (ACC), GSDMD increased ACC cell invasiveness, indicating that high GSDMD expression was associated with a poor prognosis." (PMID 36120543, 2022).
alcoholic steatohepatitis (1 paper, 2024). "In other words, such nanobiologics counteracted GSDMD-mediated release of pro-inflammatory cytokine IL-1β to retard progression of alcoholic steatohepatitis." (PMID 39253076, 2024). "During progression of alcoholic steatohepatitis, GSDMD pore formation is critical to the excessive release of IL-1β from ethanol or acetaldehyde-stimulated macrophages." (PMID 39253076, 2024).
anaplastic thyroid cancer (1 paper, 2024). "In this study, we found that ibuprofen induces pyroptosis in anaplastic thyroid cancer cells via the NLRP3/ASC/GSDMD pathway, which activates the NLRP3 inflammasome and cleaves GSDMD in vitro and in vivo." (PMID 37999895, 2024).
Anxiety (1 paper, 2024). Intense feelings of nervousness, tension, or panic often arise in response to interpersonal stresses. "Collectively, these behaviors suggest that GSDMD‐deficient mice exhibit autism‐like behaviors, such as anxiety, exploratory deficits, and social deficits." (PMID 39033542, 2024). "The results of the Y‐maze test showed that GsdmdcKO‐Nes mice were more inclined to enter the old arm without exploring the new arm compared to Gsdmdfl/fl mice, suggesting that GSDMD deficient mice exhibit anxiety‐like behavior and deficits in exploratory ability." (PMID 39033542, 2024).
arthropathy (1 paper, 2021). Any disorder of the joints. "GSDMD plays a key role in the pathogenesis of PTOA, but not STIA, suggesting that its actions in experimental arthropathy are tissue context-specific." (PMID 34784954, 2021).
autism (1 paper, 2024). Persistent deficits in social interaction and communication and interaction as well as a markedly restricted repertoire of activity and interest as well as repetitive patterns of behavior. "Here, the study reports that the absence of GSDMD‐mediated pyroptosis results in defective DNA damage sensor pathways accompanied by aberrant neurogenesis and autism‐like behaviors in adult mice." (PMID 39033542, 2024).
bacterial meningitis (1 paper, 2025). Inflammation of the membranes surrounding the brain and spinal cord due to a bacterial infection. "The identification of this shared mechanism not only advances our understanding of bacterial meningitis pathogenesis but also suggests potential therapeutic strategies targeting GSDMD activation in brain endothelial cells." (PMID 40821830, 2025).
benign prostate hyperplasia (1 paper, 2024). "In this study, P2X7R, NEK7, and GSDMD-NT expression levels were detected in prostate tissues from benign prostate hyperplasia (BPH) patients and experiment autoimmune prostatitis (EAP) mice." (PMID 38993566, 2024).
Blindness (1 paper, 2024). Blindness is the condition of lacking visual perception defined as a profound reduction in visual perception. "Corneal fibrosis is a significant cause of blindness indicating that additional strategies, beyond GsdmD inhibition, are likely needed to restore corneal clarity." (PMID 39496510, 2024).
brain cancer (1 paper, 2023). A primary or metastatic malignant neoplasm affecting the brain. "The extracellular GSDMD-N may also benefit patients with brain cancer who are susceptible to bacterial infection because GSDMD is an antibacterial peptide." (PMID 36699618, 2023).
bronchiectasis (1 paper, 2025). Segmental, irreversible dilation of the bronchial tree resulting in the accumulation of secretions which leads to obstruction. "Moreover, because the current GSDMD-targeting agents fail to effectively block GSDMD activation in patient-derived neutrophils, whether GSDMD constitutes a viable therapeutic target for controlling NETosis in bronchiectasis warrants further investigation." (PMID 41395250, 2025).
Burkholderia Infections (1 paper, 2021). Infections with bacteria of the genus BURKHOLDERIA. "Activation of GSDMD and inflammasome dependent pyroptosis is protective against Burkholderia infection in mice, with GSDMD also functioning to directly kill Burkholderia." (PMID 34821529, 2021). "We postulate that GSDMD activation in the epidermal layers beneath the stratum corneum during prolonged Burkholderia infection could trigger extensive cell death and extrusion of the keratinocytes into the stratum corneum." (PMID 34821529, 2021).
candidiasis (1 paper, 2021). Infection with the organism Candida. "Here we show disruption of GSDMD, a known inflammasome target and key pyroptotic cell death mediator, paradoxically alleviates candidiasis, improving outcomes and survival of Candida-infected mice." (PMID 34795266, 2021). "GSDMD inhibition alleviated candidiasis by preventing C. albicans escape from macrophages while maintaining inflammasome-dependent but GSDMD-independent IL-1β production for anti-fungal host defenses." (PMID 34795266, 2021). "However, WT and Gsdmd-/- macrophages generated the same amount of TNFα and IL-6 after Candida infection, supporting the notion that the expression and secretion of these cytokines were GSDMD-independent." (PMID 34795266, 2021).
carotid atherosclerosis (1 paper, 2024). A thickening and loss of elasticity of the walls of carotid arteries that occur with formation of atherosclerotic plaques. "GSDMD, CASP1, NLRC4, AIM2, and IL18 were the key pyroptosis related genes, which might provide a new sight in the prevention of fatal strokes in advanced carotid atherosclerosis." (PMID 38167983, 2024).
clear cell renal cell carcinoma (1 paper, 2023). "The expression of GSDMD in clear cell renal cell carcinoma and its effect on its biological function was investigated by means of a bioinformatics platform database, clinical data analysis, and in vitro cytological experiments." (PMID 37483501, 2023). "We compared the expression of GSDMD in 539 cases of clear cell renal cell carcinoma and 72 cases of normal kidney tissue through TCGA database screening." (PMID 37483501, 2023). "The results showed that the expression of GSDMD in clear cell renal cell carcinoma was significantly higher than that in normal renal tissue." (PMID 37483501, 2023). "Next, we used the GEO database to analyze the expression of GSDMD in 72 cases of clear cell renal cell carcinoma and 72 normal patient tissues and plotted ROC curves to validate the results of TCGA database." (PMID 37483501, 2023). "The results of bioinformatics analysis showed that the expression of GSDMD in clear cell renal cell carcinoma was significantly correlated with patient stage and overall survival, and the tumor with high expression of GSDMD had a worse stage and overall survival." (PMID 37483501, 2023). "The differential expression of GSDMD may play an important role in the metastasis and invasion of clear cell renal cell carcinoma." (PMID 37483501, 2023).
Co-infection (1 paper, 2026). "Inhibition of GSDMD-mediated pyroptosis may represent a viable therapeutic approach to alleviate disease severity and improve outcomes in lethal co-infection." (PMID 41927528, 2026). "Co-infection significantly enhanced the cleavage of caspase-1 and GSDMD in RAW264.7 cells." (PMID 41927528, 2026).
cognitive decline (1 paper, 2024). "In conclusion, data in current study demonstrates the involvement of the Casp11 and GSDMD in the breakdown of the blood–brain barrier, the enhance of neuroinflammation, and the loss of synaptic connections in the hippocampus, all of which are associated with the cognitive decline." (PMID 39179968, 2024).
Constipation (1 paper, 2025). Infrequent or difficult evacuation of feces. "This study found that GSDMD expression was significantly elevated in the constipation model group, consistent with the inflammatory state of the intestine associated with constipation." (PMID 41050658, 2025). "The downregulation of CASP3, GSDMD, and MLKL expression observed after HP treatment suggests that its protective effects on epithelial barrier integrity and anti-inflammatory properties may have broader therapeutic applications beyond constipation." (PMID 41050658, 2025).
contact dermatitis (1 paper, 2021). An inflammatory skin condition caused by direct contact between the skin and either an irritating substance or an allergen. "Whether or not gasdermin D participates in pro‐inflammatory cell death by pyroptosis in the context of allergic and/or irritant contact dermatitis remains open." (PMID 34322217, 2021).
corneal disease (1 paper, 2023). "Overall, these findings support a role for NLRP3 and caspase-1 in regulating bacterial killing and corneal disease severity with no apparent role for NLRC4 and no requirement for GSDMD, GSDME, or neutrophil elastase." (PMID 37730693, 2023).
Crush Syndrome (1 paper, 2025). Severe systemic manifestation of trauma and ischemia involving soft tissues, principally skeletal muscle, due to prolonged severe crushing. "Pathologically, it contributes to crush syndrome-induced kidney injury via myoglobin-triggered M1 macrophage polarization through the RIG-I/Caspase-1/GSDMD axis, demonstrating its multifaceted roles in immunity and disease." (PMID 40491921, 2025).